COL1A1 (collagen type I alpha 1 chain)
Diseases named in the same sentence as COL1A1 in open-access papers (continued):
Sharing a sentence is not in itself a finding about the gene and the disease.
tumor (continued). "In this study, we decided to use the collagen type 1 α1 (COL1A1) gene as a tumor-related gene from the results of the triple-combination arrays." (PMID 24552139, 2014). "Taken together, as for our 48 samples, although COL1A1 mRNA is usually up-regulated in tumor tissues, there is a small group of tumors that has down-regulated mRNA expression mainly due to promoter methylation." (PMID 24552139, 2014). "Expression array revealed that COL1A1 gene expression was markedly decreased in tumor tissues (log2 ratio –1.1)." (PMID 24552139, 2014). "Smad7 overexpression has previously been shown to decrease COL1A1 mRNA levels in normal human fibroblasts, which supports our results obtained in fibroblasts directly co-cultured with tumour cells." (PMID 24090133, 2013). "Notably, the enrichment of collagen and integrin interactions (e.g., COL1A1_ITGA1) further indicates that APOE+ macrophages organize the tumor stroma elements to facilitate tumor progression and immune evasion." (PMID 40303328, 2025). "While the authors did not explicitly designate COL1A1+ ECs as EndMT-derived CAFs, the functional parallels—tumor promotion, metastatic association, immune pathways, and worse outcomes—support the concept and its relevance to CAF biology." (PMID 41154806, 2025). "Together, these findings suggest that COL1A1 could contribute to KIRC progression through effects on the tumor microenvironment and potential influences on cancer stem cell behavior, such as proliferation, drug resistance, and immune evasion." (PMID 40851082, 2025). "Interactions via the Cd44/Col14a1 and Cd44/Col1a1 pathways highlight the role of immune cells in monitoring the tumour microenvironment, which may be involved in modulating the inflammatory response and promoting tissue repair." (PMID 40046334, 2025). "The findings indicate that COL1A1 may be involved in tumor cell proliferation, migration, invasion, and EMT, and is associated with activation of the PI3K/Akt pathway." (PMID 40851082, 2025). "Mechanistically, these observations align with bioinformatic analyses highlighting PDGFRβ as an upstream regulator of multiple downstream effectors—PPARγ, VEGFA, ANG-2, VIM, COL1A1, and Cadherins all integral to tumor progression, angiogenesis, and cellular plasticity." (PMID 40282535, 2025). "Theses 13 genes (e.g., COL1A1, POSTN, ASPN, PDGFRA, MUC4, SPARC), implicated notably in EMT and cancer progression, were found to be highly expressed in depth of tumor ID15 and ID08, near the invasive margin." (PMID 40076457, 2025). "Additionally, COL1A1 expression was significantly elevated in CTCs compared to primary tumor lesions, and further enriched in CTC clusters relative to single CTCs49." (PMID 40093812, 2025). "Furthermore, spiking experiments were conducted to investigate the impact of COL1A1 knockdown on NE+ tumor cells." (PMID 40093812, 2025). "Similarly, ITGAV, PDGFC, PDGFD, and COL1A1—the most abundant collagen in human tissues—are often highly expressed in tumor cells, and inhibiting their expression can effectively suppress cell proliferation, migration, and invasion." (PMID 41227351, 2025). "The tumor-promoting effects of COL1A1 may be partly mediated through its activation of the WNT/PCP signaling pathway, which stimulates JNK-dependent cytoskeletal reorganization—a known driver of invasive progression." (PMID 40507957, 2025). "Further exploration of the interactions among COL1A1, immune cells, and extracellular matrix components in the tumor microenvironment may provide valuable information for a more comprehensive understanding of its role in KIRC progression." (PMID 40851082, 2025). "This upregulation implies that COL1A1 may not only drive tumor cell dissemination into the bloodstream but also promote the clustering of single CTCs into CTCs clusters with enhanced metastatic potential." (PMID 40093812, 2025).
tumor (continued). "Moreover, tumor-associated (MKI67) and CAF-related (FAP, Fibronectin, COL1A1) genes were downregulated in the FAP/IL-15 CAR-T group compared to other groups." (PMID 41455698, 2025). "Visual inspection of IMC images with COL1A1 and tumor marker staining pointed out the presence of diverse collagen structures, different levels of collagen fiber alignment, and different levels of tumor–stroma demarcation from perfect segregation to completely mixed areas." (PMID 41042551, 2025). "We speculate that spindle-shaped FOXL2+COL1A1+ cells may behave more like fibroblasts and contribute to collagen synthesis, deposition, and remodeling of the ECM, whereas small round FOXL2+COL1A1+ cells may represent tumor cells undergoing EMT." (PMID 41042551, 2025). "Although ECM components (including specific collagens such as Col1a1/2, Col3a1) have shown upregulated expression in some human malignancies and tumor microenvironments, in our rodent model these ECM changes likely represent adaptive responses to thermal stress rather than pre-neoplastic events." (PMID 41301502, 2025). "Immunofluorescence (IF) staining of tumor and adjacent normal tissue sections, using COL1A1 as a pan‐fibroblast marker and MMP11 as a specific marker, confirmed the predominant presence of MMP11+ mCAFs within the TME, supporting their potential functional relevance." (PMID 40552583, 2025). "Individual real‐time fluorescence quantification showed that KRT17 gene expression levels were significantly increased in tumor tissues from 145/180 patients with EC, and COL1A1 gene expression levels were significantly increased in tumor tissues from 152/180 patients." (PMID 38979664, 2024). "Targeting FN1, COL1A1, or downstream signaling pathways may offer new therapeutic opportunities for inhibiting tumor growth and improving treatment responses." (PMID 39065771, 2024). "Notably, COL1A1, COL1A2, and FAP were closely associated with CAF-mediated functions related to carcinogenesis and tumor metastasis." (PMID 39034310, 2024). "Similarly, progression-free survival (PFS) exhibited a trend comparable to OS, with patients exhibiting higher tumor stages and COL1A1 expression showing significantly reduced PFS." (PMID 39845977, 2024). "Taken together, these studies reaffirm our bioinformatics-based analysis and suggest that these extracellular matrix genes (CDH3, COL11A1, COL1A1, COL17A1, KRT19, ITGA2, LAMC2, and SULF1) are highly associated with PDAC tumor carcinogenesis and peritoneal metastasis." (PMID 39682235, 2024). "Elevated expression of COL1A1 was positively correlated with tumor metastasis and LNM." (PMID 39191749, 2024). "While in vivo follow up examining Col1a1-dependent Ccn2 loss in mice support the angiogenesis result, the impacts on tumor progression were not discussed." (PMID 38525245, 2024). "It has been shown that silencing the COL1A1 gene leads to favorable tumor characteristics in TNBC." (PMID 39273393, 2024). "Similarly, in tumor subgroups with decreased CD8+ T cells (HR=1.55, p=0.0045) and decreased CD4+ T cells (HR=1.47, p=0.018), high COL1A1 expression was significantly associated with poor prognosis in OC." (PMID 39845977, 2024). "CDKN1 and COL1A1 have terms including “increased tumor incidence”." (PMID 36674696, 2023). "Notably, this signature includes ECM proteins that can strongly influence tumour progression, such as collagen 1 (COL1A1)." (PMID 38223308, 2023). "Arina and colleagues found that CAFs expressing collagen type I alpha 1 (Col1a1) and alpha-smooth muscle actin (αSMA), two CAF-associated markers, originated mainly from precursors located in the tumour microenvironment, while the contribution from bone marrow circulating precursors was infrequent." (PMID 35767180, 2023).
tumor (continued). "In additions, clusters 4, 7 and 10 expressed a variety of collagen proteins including COL1A1, COL1A2, COL3A1, COL6A1 and COL6A3, which have been previously linked to abilities of proliferation, invasion, metastasis and drug resistance of tumor cells." (PMID 37644609, 2023). "Of those collagens that were differentially regulated, all were down-regulated in patient-derived tumour samples compared to matched non-tumour samples, ranging from 1.7-fold for type I collagen α1 chain (COL1A1) to 18.1-fold for type VI collagen α6 chain (COL6A6)." (PMID 37397358, 2023). "Finally, we also found that COL1A1+ CAFs mediated the interaction with tumor cells through collagen proteins." (PMID 37021816, 2023). "In GC, COL1A1 can promote tumor progression as a promising prognostic target." (PMID 37461041, 2023). "In addition, let-7i acts as a tumor suppressor, preventing invasion and metastases of GC cells, promoting the inactivation of collagen, type I, alpha 1 (COL1A1)." (PMID 37179825, 2023). "We detected 24 genes across the tumor tROIs that showed a high CV (i.e., were among the genes with the top 20% highest CV in seven out of seven cases), such as multiple collagens (COL1A1, COL1A2, COL3A1, COL5A1, COL5A2), S100A8, S100A9, FN1, or Early growth response protein 1 (EGR1)." (PMID 37511126, 2023). "Quantitative PCR (qPCR) of the tumor tissue samples revealed that doxycycline induced Meflin expression in Col1a1+ stromal cells, representing CAFs, in tumors developed in Meflin-TO mice administered doxycycline, but not in control mice that lack the Meflin-Cre allele." (PMID 35236758, 2022). "Meanwhile, the low COL1A1 expression was thought to inhibit tumor proliferation and metastasis." (PMID 35669725, 2022). "Moreover, we recently demonstrated that inhibition of COL1A1 expression within the tumor cells reprogramed the tumoral microenvironment and inhibited tumor invasion and progression." (PMID 36276147, 2022). "The increase of APOB expression may promote the interaction between DCN and COL1A1, so as to promote tumor metastasis." (PMID 36428687, 2022). "Notably, the vCAFs were substantially reduced in Atf4Δ/Δ mice, and Col1a1 and Col1a2 were significantly downregulated only in the vCAF subcluster in the small tumours in Atf4Δ/Δ mice." (PMID 35654839, 2022). "COL1A1 can form collagen fibers; as an effective component of bone marrow, it is also involved in the proliferation, metastasis, and angiogenesis of a variety of tumor cells." (PMID 36211008, 2022). "This involvement in extracellular matrix-related pathways strengthens the case that the mechanism of COL1A1 may involve tumor cell interaction with its outer environment." (PMID 36873459, 2022). "COL1A1 is considered a downstream product of cytoglobin, which is related to tumor biology and contributes to the adaptive response to oxidative stress and hypoxia/reoxygenation events, thereby promoting lung tumor invasiveness, metastasis, and resistance to treatment." (PMID 35846148, 2022). "Thus, we further explored if the COL1A1 expression is correlated with the degree of immune cell infiltration in different types of tumor by TIMER database." (PMID 35789341, 2022). "Furthermore, MS-proteomic analysis of the tumours detected Col1a1 and Col1a2 peptides containing 13C5-proline (datasheet ‘H/L ratio collagen peptides’)." (PMID 35760868, 2022). "Moreover, these parameters were further reduced in Col1a1-Krm2-transgenic NSG mice by tumor cell injection." (PMID 35158823, 2022). "Additionally, the COL1A1 inhibitor only decreased spheres formation of tumor cells when they co-cultured with CAFs." (PMID 35322024, 2022). "With the increase of tumor grade, the expression of COL1A1 increased accordingly." (PMID 35789341, 2022).
tumor (continued). "In this research, we used TCGA independent data sets and GEO database to assess the expression of COL1A1 and the prognosis in kinds of tumor, showing that the expression of COL1A1 of multiple cancers is significantly different between tumors and normal tissues." (PMID 35789341, 2022). "The results suggest that COL1A1 is related with tumor immune infiltration of LGG." (PMID 35789341, 2022). "To investigate whether COL1A1 expression is correlated to the prognosis of tumor, we downloaded the clinical data of tumors from TCGA and CGGA." (PMID 35789341, 2022). "Moreover, we can conclude from the relationship between the expression level of COL1A1 and certain markers of immune cell that COL1A1 plays a critical role in regulating tumor immunology of LGG." (PMID 35789341, 2022). "Also, we observed that intracranial implantation of Col1a1-knockdown cells resulted in decreased tumor growth and progression when compared to controls." (PMID 35750880, 2022). "The extracellular matrix in tumour was also determined by COL1A1 staining." (PMID 33654093, 2021). "Recent studies have shown that CD276 and B7-H4 have a co-inhibitory role on T-cells, participating in tumor cell immune evasion, whose overexpression has a significant relationship with poor prognosis in tumor patients, which was consistent with the prognostic value of COL1A1." (PMID 33850663, 2021). "In conclusion, we found that COL1A1 could be a marker for different cancers and is critical for tumor immune microenvironments." (PMID 34395525, 2021). "However, there is no pan-cancer analysis to comprehensively elucidate the potential role of COL1A1 in various tumor types." (PMID 34395525, 2021). "However, the effects of circ_0004370/miR-1301 3p/COL1A1 axis on tumor metastasis cannot be done currently due to the laboratory conditions." (PMID 33506107, 2021). "In addition, COL1A1 was positively correlated with the abundance of CAFs, macrophages, and tumor-infiltrating lymphocytes." (PMID 34395525, 2021). "Furthermore, we divided the tumor sites into two groups according to COL1A1 expression and found that CD276 levels were positively correlated with the level of COL1A1." (PMID 33850663, 2021). "We further analyzed the expression of COL1A1 in different tumor stages." (PMID 34395525, 2021). "The study confirmed the essential role of Col1A1 and tumor fibrosis in the prognosis of ccRCC." (PMID 34539753, 2021). "Expression intensities of SPARC, COL1A1, COL5A1, COMP, IBSP, and THBS4 were interpreted in tumor stroma, as they were associated with ECM-related pathways, and the expression intensity of SORD was interpreted in tumor cells, as it was associated with the EMT pathway." (PMID 34503278, 2021). "Col1a1 mRNA expression was also decreased in tumor tissues from Bgn KO mice." (PMID 33966638, 2021). "Given the aberrant expression of COL1A1 in tumor tissues, we supposed that type I collagen might play a role through integrins signals in tumor development." (PMID 34319913, 2021). "Therefore, we designed a tumour-agnostic approach to test the potential of COL1A1 expression as a biomarker for primary pan-cancer survival." (PMID 33980846, 2021). "This study suggests that tumor epithelial BMP1/COL1A1 expression may be a positive prognostic factor, although bulk fibrillar collagen level was shown to correlate negatively with patient survival." (PMID 33879793, 2021). "The higher concentrations of COL1A1 were significantly correlated with the peripheral type tumor (P < 0.001), larger diameter of the tumor (P = 0.028), occurrence of lymph node metastases (P < 0.001) and distant metastases (P = 0.001), higher TNM stage (III, IV) (P = 0.049), and smoking (P < 0.001)." (PMID 34475986, 2021). "Circulating bone formation (P1NP) and bone resorption (CTX) markers were not different between genotypes at 5 and 15 weeks and mRNA expression of the major collagens Col1a1, Col1a2 and Col3a1 appeared comparable in tumor-bearing bones at 5 weeks and in primary OS cells." (PMID 32686768, 2020).
tumor (continued). "Remarkably, circCSPP1 could upregulate the mRNA levels of COL1A1, and the tumor promoter role of circCSPP1 in cell migration and invasion could be almost offset by downregulating COL1A1." (PMID 32612946, 2020). "Through this work, we identified COL1A1 as a key biomarker within the LSCC tumor microenvironment." (PMID 33062455, 2020). "By using immunohistochemistry, we found co-occurrence of stromal CAFs and senescent TC cells at the tumor invasive front, where deposition of collagen (COL1A1) and expression of lysyl oxidase (LOX) enzyme were also detected, in association with features of local invasion." (PMID 31906302, 2020). "In this study, using bioinformatics analysis of publicly-available HCC microarray data from Gene Expression Omnibus (GEO) and RNAseq data from The Cancer Genome Atlas (TCGA) database, we determined that COL1A1 is significantly upregulated in HCC tumor tissues in comparison to normal tissues." (PMID 31181620, 2019). "The increased availability of Mmp2 and Mmp12 as well as their substrates Col1a1, Col4a1, Col6a1 and LamC2 could indicate that the tumour cells generated foremost collagens, which can be cleaved by these Mmps." (PMID 30603057, 2018). "Next, we asked which growth factors might facilitate tight cell adhesion by synthesis of COL1A1 in tumor spheroids." (PMID 28423507, 2017). "We found COL1A1 to be upregulated in the canine tumour stroma by RT-qPCR." (PMID 28531107, 2017). "This might be due to insufficient sample number taken into analysis, existence of another promoter controlling COL1A1 expression or presence of a potent factor that affects COL1A1 mRNA content more profoundly than DNA methylation, e.g., tumour hypoxia." (PMID 28258342, 2017). "We found that losartan inhibited COL1A1 mRNA expression in tumor spheroids." (PMID 28423507, 2017). "Collagen 1A1 (COL1A1), RNA-binding and pre-mRNA Processing Factor (PRPF40A), and Uncoupling Protein 2 (UCP2) were identified as downstream effectors of cytoglobin (CYGB), which was shown implicated in tumour biology." (PMID 28258342, 2017). "Finally, when celecoxib was used prior to tumor formation, PyMT/Col1a1 tumors were fewer and smaller than in untreated animals." (PMID 27000374, 2016). "Among the 48 tumor tissues, 20 (41.7%) showed COL1A1 promoter methylation." (PMID 24552139, 2014). "Although a significant correlation was not indicated in the multivariate analysis of this small cohort, epigenetic down-regulation of COL1A1 mRNA expression in tumor tissues might be a candidate prognostic factor of HCC." (PMID 24552139, 2014). "Above all, COL1A1 promoter methylation in the tumor tissue was confirmed." (PMID 24552139, 2014). "To verify our hypothesis, we first confirmed that COL1A1 mRNA expression and COL1A1 protein were decreased in the study patient’s tumor tissue." (PMID 24552139, 2014). "As a result, we hypothesized that decreased expression of COL1A1 gene in tumor tissue was influenced by promoter methylation." (PMID 24552139, 2014). "Overall, by defining COL1A1+ ECs as an EndMT-featured endothelial state in GC and connecting EdMTS to metastasis patterns, immune dysregulation, and adverse prognosis, this study provided patient-level evidence that EndMT-like endothelial remodeling contributes to tumor progression." (PMID 41154806, 2025). "Additionally, collagen proteins (COL1A1, COL1A2, COL3A1, COL11A1) were linked to tumor progression and metastasis, while chaperonin-containing TCP1 (CCT) complex proteins and microtubule-associated proteins (TUBA1C, TUBB) were implicated in cytoskeletal organization and chemotherapy resistance." (PMID 40867231, 2025). "Similar to luminal cluster 2 in primary tumour, cluster 3 in lung mets, was enriched in a proliferation gene signature (Ran, Cks1b, and Cks2), whereas cluster 2 (homologous to cluster 3 in primary tumour), expressed a mesenchymal-like gene set (Col18a1, Vcam1, Col1a1, Vim, Sparc)." (PMID 38238426, 2024).